ARHGAP33 (Rho GTPase activating protein 33)
Description:
May be involved in several stages of intracellular trafficking. Could play an important role in the regulation of glucose transport by insulin. May act as a downstream effector of RHOQ/TC10 in the regulation of insulin-stimulated glucose transport (By similarity).
Synonyms: SNX26; TCGAP; FLJ39019; NOMA-GAP
Tractability: Antibody: its Gene Ontology location is reachable by antibodies, with medium confidence; the Human Protein Atlas places it where antibodies can reach. PROTAC: its protein half-life has been measured.
Gene: Protein-coding gene on chromosome 19 (35,774,532 to 35,788,822, forward strand). Ensembl gene ENSG00000004777.
Subcellular location (Human Protein Atlas): Plasma membrane; Actin filaments; Cytosol
Pathways (Reactome):
Signal Transduction: CDC42 GTPase cycle; RAC1 GTPase cycle; RHOQ GTPase cycle
Gene Ontology:
Molecular function: protein binding; protein kinase binding; GTPase activator activity; phosphatidylinositol binding
Biological process: regulation of dendritic spine morphogenesis; regulation of postsynapse assembly; small GTPase-mediated signal transduction; signal transduction
Cellular component: protein-containing complex; cytosol; glutamatergic synapse; postsynaptic density; cytoplasm
Genetic constraint (gnomAD): Loss-of-function variants: 57 observed, 120.53 expected, observed/expected ratio (o/e) 0.47, 90% interval 0.38 to 0.59. The upper end of that interval is the gene's LOEUF score, 0.59, which puts it in group 2 of 6, group 1 being the genes least tolerant of losing a copy. Missense variants: 1,489 observed, 1,691 expected, observed/expected ratio (o/e) 0.88, 90% interval 0.84 to 0.92. Synonymous variants: 706 observed, 731.47 expected, observed/expected ratio (o/e) 0.97, 90% interval 0.91 to 1.03.
Homologues: Orthologues: macaque ARHGAP33 (99% identical), dog ARHGAP33 (92% identical), pig ARHGAP33 (92% identical), mouse Arhgap33 (92% identical), rat Arhgap33 (91% identical), guinea pig ARHGAP33 (88% identical), chimpanzee ARHGAP33 (86% identical), rabbit ARHGAP33 (78% identical), tropical clawed frog arhgap33 (47% identical), Drosophila melanogaster CdGAPr (27% identical), Caenorhabditis elegans rrc-1 (16% identical). Paralogues in human: ARHGAP32 (41% identical), ARHGAP30 (20% identical), ARHGAP31 (19% identical).
Diseases named in the same sentence as ARHGAP33 in open-access papers:
ARHGAP33 is named in the same sentence as 18 diseases in open-access papers, as found by Europe PMC text mining. Sharing a sentence is not in itself a finding about the gene and the disease. The quoted sentences say what the papers report.
prostate carcinoma (3 papers, 2020 to 2024). A carcinoma that arises from epithelial cells of the prostate gland. "Regarding ARHGAP33, researchers have reported that it is a marker gene that can predict prognosis in prostate cancer, and ARHGAP family genes have been demonstrated to promote bladder cancer progression by establishing a tumor-promoting microenvironment." (PMID 35680563, 2022). "FAM72D, ARHGAP33, TACR2, PLEK2, and FA2H were identified as independent prognosis factors in prostate cancer patients." (PMID 32566639, 2020).
schizophrenia (3 papers, 2016 to 2024). A major psychotic disorder characterized by abnormalities in the perception or expression of reality. "In two independent studies, ARHGAP33 has been implicated in neuropsychiatric developmental disorders, such as autism spectrum disorders (ASDs) and schizophrenia." (PMID 30934641, 2019). "Consistent with this previous finding, we discovered for the first time that human ARHGAP33 is associated with schizophrenia in the present study." (PMID 26839058, 2016). "Then, we examined the possible association between schizophrenia and genetic variation in the ARHGAP33 gene by genotyping six tagging single-nucleotide polymorphisms (SNPs) located in the ARHGAP33 gene and its flanking regions." (PMID 26839058, 2016). "The decreased expression of ARHGAP33 in patients with schizophrenia may underlie the reduced brain volume." (PMID 26839058, 2016). "Importantly, human ARHGAP33 was associated with the brain phenotypes exhibited by schizophrenia patients." (PMID 26839058, 2016). "Our results that ARHGAP33 KO mice exhibited neuropsychiatric disorder-like abnormal behaviour suggest that human ARHGAP33 might be associated with schizophrenia or some other neuropsychiatric disorders." (PMID 26839058, 2016). "Furthermore, human ARHGAP33 is associated with brain phenotypes of patients with schizophrenia." (PMID 26839058, 2016). "Arhgap33 interacts with sortilin cooperatively to facilitate trafficking of TrkB to synapses which is impaired in schizophrenia." (PMID 38542311, 2024). "Using immortalized human lymphocytes, the authors showed that the expression level of ARHGAP33 was lower in 45 schizophrenia patients in comparison to 45 sex/age-matched controls." (PMID 30934641, 2019). "Human ARHGAP33 is associated with brain phenotypes and reduced SORT1 expression is found in patients with schizophrenia." (PMID 26839058, 2016). "Future work is needed to determine the precise role of ARHGAP33 in the pathophysiology of schizophrenia." (PMID 26839058, 2016). "Taken together, our present results suggest that both ARHGAP32 and ARHGAP33 may be involved in the pathophysiology of schizophrenia." (PMID 26839058, 2016). "Here the authors show that ARHGAP33 interacts with SORT1 to regulate TrkB trafficking, the dysfunction of which impairs synapse development and leads to schizophrenia-related behavioural abnormalities in mice." (PMID 26839058, 2016). "Interestingly, correlated decreases in ARHGAP33 and SORT1 expression levels are observed in the peripheral lymphocytes of schizophrenia patients." (PMID 26839058, 2016). "Furthermore, a correlated decrease in the ARHGAP33 and SORT1 expression levels was observed in the peripheral lymphocytes of schizophrenia patients." (PMID 26839058, 2016). "In this respect, ARHGAP33 and ARHGAP32 as well as SORT1 are unique in that they are regulators of intracellular protein trafficking, highlighting a novel role of the SNX-related proteins in the pathophysiology of schizophrenia." (PMID 26839058, 2016).
autism (2 papers, 2018 to 2022). Persistent deficits in social interaction and communication and interaction as well as a markedly restricted repertoire of activity and interest as well as repetitive patterns of behavior. "Two of genes with SLP < −3 for the problem drinking phenotype are also possibly implicated in autism risk, ARHGAP33 (SLP = −3.69) and CDH9 (SLP = −4.59)." (PMID 33893496, 2022). "Although no gene reached formal significance levels, it is possibly of some interest that three genes potentially related to autism were each individually significant at P < 0.001: FOXP1, ARHGAP33 and CDH9." (PMID 33893496, 2022). "No gene was formally significant after correction for multiple testing, but three genes possibly related to autism were significant at P < 0.001, FOXP1, ARHGAP33 and CDH9, along with VGF which may also be of psychiatric interest." (PMID 33893496, 2022).
Cognitive impairment (1 paper, 2024). Abnormal cognition is characterized by deficits in thinking, reasoning, or remembering. "Additionally, individual and group level analyses identified the Arhgap33 phosphopeptide as an indicator of BINT-induced cognitive impairment predominantly in rTg4510 mice." (PMID 38542311, 2024).
metabolic syndrome (1 paper, 2024). A cluster of metabolic risk factors for CARDIOVASCULAR DISEASES and TYPE 2 DIABETES MELLITUS. "Additionally, Arhgap33 displayed high diagnostic prediction of metabolic syndrome in patients with polycystic ovarian syndrome, which may be due to disrupted regulation of glucose transport, supporting its role in metabolic disruption." (PMID 38542311, 2024).
Obesity (1 paper, 2025). Accumulation of substantial excess body fat. "However, four of the 24 common microglial DEGs were regulated in opposite directions by obesity in males and females (Unc13a, Atp1a3, and Arhgap33 upregulated in females and downregulated in males; Rbm47 upregulated in males and downregulated in females)." (PMID 41310161, 2025).
tumour (3 papers, 2019 to 2022). "For Arhgap33, staining was associated with neurites, which were generally displaced by tumour-associated gliosis (reactive change of glial cells in response to damage to brain tissue), resulting in overall lower levels in regions proximal to tumour nests." (PMID 31121957, 2019). "Of the proteins validated orthogonally by fmIHC, in situ analysis suggested that Arhgap33 and Claudin-11 were probably less abundant in TAB due to displacement of neural tissue by the expanding tumour." (PMID 31121957, 2019).
ARHGAP33 also shares sentences with these, for which no sentence is quoted: bladder cancer (1 paper); cancer (1); cognitive decline (1); COVID-19 (1); developmental delay (1); diabetes (1); epilepsy (1); kidney damage (1); microcephaly (1); polycystic ovarian syndrome (1); tauopathy (1).